LINC01303 (long independently transcribed non-coding RNA 1303)
Gene: Long non-coding RNA gene on chromosome 14 (61,546,783 to 61,618,974, reverse strand). Ensembl gene ENSG00000250548.
Diseases named in the same sentence as LINC01303 in open-access papers:
LINC01303 is named in the same sentence as 3 diseases in open-access papers, as found by Europe PMC text mining. Sharing a sentence is not in itself a finding about the gene and the disease. The quoted sentences say what the papers report.
gastric cancer (1 paper, 2019). A primary or metastatic malignant neoplasm involving the stomach. "To elucidate the role of the LINC01303/miR‐101‐3p/EZH2 axis in gastric cancer, we performed experiments using the miR‐101‐3p inhibitor and EZH2 siRNA." (PMID 31497936, 2019). "Therefore, we analysed the TCGA data to find that LINC01303 is significantly up‐regulated in gastric cancer tissues." (PMID 31497936, 2019).
ovarian carcinoma (1 paper, 2020). A malignant neoplasm originating from the surface ovarian epithelium. "In addition, lncRNA PTAR, SPRY4‐IT1 and LINC01303 also sponge miR‐101‐3p to prompt cell proliferation and metastasis in GC and ovarian cancer." (PMID 32147945, 2020).
tumor (4 papers, 2019 to 2023). "High expression of LINC01303 was associated with patient age (P = .018), larger tumour size (P = .001), depth of invasion (P = .010) and AJCC stage (P = .001)." (PMID 31497936, 2019). "We used qRT-PCR analysis to examine the expression of LINC01303 in OSCC tumor tissues and their corresponding normal tissues to investigate the potential function of LINC01303 in OSCC." (PMID 34912458, 2021). "To confirm that LINC01303 participated in tumor developmental process through miR-429/ZEB1 axis, we carried out cotransfection experiments." (PMID 34912458, 2021). "Consistent with the finding that LINC01303 silencing inhibited tumor metastasis in vivo, E-cadherin expression was upregulated in the sh-LINC01303 group, whereas vimentin was downregulated." (PMID 34912458, 2021). "LINC01303 is conveniently located on the 14q23.1 chromosome; it is highly expressed in gastric cancer and inhibits tumor occurrence by mediating miR-101-3p." (PMID 34912458, 2021). "We also analysed the mRNA expression levels of LINC01303 in 30 pairs of GC tissues and adjacent non‐tumour tissues by real‐time PCR assay." (PMID 31497936, 2019). "The results showed that the expression of LINC01303 in GC tissues was significantly higher than that in non‐tumour tissues (P < .05)." (PMID 31497936, 2019). "However, upregulated NUSAP1 expression partially reversed the effect of LINC01303-KD, leading to the increased tumor volume and shorten survival." (PMID 36982952, 2023). "In addition, ZEB1 expression was positively correlated with LINC01303, and its downregulation reversed tumor phenotype mediated by LINC01303 overexpression in vitro and in vivo." (PMID 34912458, 2021). "Furthermore, to determine the effects of LINC01303 on OSCC tumor growth in vivo, LINC01303-knockdown (sh-LINC01303) or control (sh-NC) TSCCA cells were injected subcutaneously into nude mice." (PMID 34912458, 2021). "The role of LINC01303 in OSCC can be better evaluated by using an in situ tumor model." (PMID 34912458, 2021). "As an emerging tumor biomarker, LINC01303 has been extensively studied, but its role in OSCC is unknown." (PMID 34912458, 2021). "Overall, the results indicate that LINC01303 is an important oncogenic regulator in the development of tumours in GC and may be a potential target for clinical diagnosis and treatment of GC." (PMID 31497936, 2019). "The role of LINC01303 in the growth of TSCCA and SCC-25 was examined by CCK-8 assay, colony formation, transwell invasion assay in vitro, and xenograft tumor experiment in vivo." (PMID 34912458, 2021). "Univariate Cox regression analysis of clinical indicators revealed that T stage, N stage, M stage, pathologic stage, age, histological type, residual tumor, HSPA8P4, PHC1P1, RBMS1P1, LINC01303, and MSC-AS1 were meaningful, and the expression level of COL5A2 was also significant." (PMID 36447214, 2022). "Whether LINC01303 serves a function in the tumor progression of OSCC has not been reported." (PMID 34912458, 2021).